AKAP7 (A-kinase anchoring protein 7)
Description:
Probably targets cAMP-dependent protein kinase (PKA) to the cellular membrane or cytoskeletal structures. The membrane-associated form reduces epithelial sodium channel (ENaC) activity, whereas the free cytoplasmic form may negatively regulate ENaC channel feedback inhibition by intracellular sodium. Targets the cAMP-dependent protein kinase (PKA) to the plasma membrane, and permits functional coupling to the L-type calcium channel. The membrane-associated form reduces epithelial sodium channel (ENaC) activity, whereas the free cytoplasmic form may negatively regulate ENaC channel feedback inhibition by intracellular sodium.
Synonyms: AKAP15; AKAP18
Tractability: Antibody: its Gene Ontology location is reachable by antibodies, with high confidence. PROTAC: its protein half-life has been measured.
Gene: Protein-coding gene on chromosome 6 (131,135,467 to 131,283,535, forward strand). Ensembl gene ENSG00000118507.
Subcellular location: Nucleus; Cytoplasm; Lateral cell membrane (Isoform Alpha); Apical cell membrane (Isoform Beta)
Subcellular location (Human Protein Atlas): Vesicles
Gene Ontology:
Molecular function: protein binding; protein kinase A binding; protein kinase A regulatory subunit binding; protein kinase binding
Biological process: modulation of chemical synaptic transmission
Cellular component: cytoplasm; cytosol; protein-containing complex; hippocampal mossy fiber to CA3 synapse; nucleus
Genetic constraint (gnomAD): Loss-of-function variants: 25 observed, 26.26 expected, observed/expected ratio (o/e) 0.95, 90% interval 0.69 to 1.33. The upper end of that interval is the gene's LOEUF score, 1.33, which puts it in group 5 of 6, group 1 being the genes least tolerant of losing a copy. Missense variants: 260 observed, 277.33 expected, observed/expected ratio (o/e) 0.94, 90% interval 0.85 to 1.04. Synonymous variants: 90 observed, 98.67 expected, observed/expected ratio (o/e) 0.91, 90% interval 0.77 to 1.09.
Homologues: Orthologues: chimpanzee AKAP7 (99% identical), pig AKAP7 (82% identical), macaque AKAP7 (82% identical), dog AKAP7 (79% identical), rat Akap7 (75% identical), guinea pig AKAP7 (71% identical), mouse Akap7 (71% identical), rabbit AKAP7 (69% identical), tropical clawed frog akap7 (41% identical). Paralogues in human: AKAIN1 (4% identical).
Diseases named in the same sentence as AKAP7 in open-access papers:
AKAP7 is named in the same sentence as 17 diseases in open-access papers, as found by Europe PMC text mining. Sharing a sentence is not in itself a finding about the gene and the disease. The quoted sentences say what the papers report.
viral infections (4 papers, 2015 to 2024). "AKAP7 is a gene encoding a protein kinase A-binding scaffolding molecule associated with a cellular regulatory pathway during viral infections." (PMID 38741036, 2024). "Despite PDE12, ENPP1 and AKAP7 degrades 2′-5′ oligoadenylates in vitro their importance during viral infection, has yet to be reported." (PMID 26113370, 2015). "A-kinase-anchoring protein 7 (AKAP7), a mammalian counterpart, could possibly limit tissue damage from excessive or prolonged RNase L activation during viral infections or from self-double-stranded RNAs that activate OAS." (PMID 34372695, 2021).
ischemic stroke (2 papers, 2017 to 2021). A stroke disorder caused by obstruction of blood flow to the brain, due to thrombotic (local blood clot formation) or embolic (due to a blood clot or other material traveling from another site) event. "Collectively, our results suggest that early expression levels of AKAP7 in the peripheral immune system are predictive of the development of BBB disruption in the days following ischemic stroke." (PMID 28446746, 2017). "Furthermore, a study identified that the expression levels of A-kinase anchoring protein 7 (AKAP7) were high in the peripheral blood (lymphocyte), and thus might be considered to identify BBB breakdown during ischemic stroke or post-stroke." (PMID 34489623, 2021).
Stroke (2 papers, 2017 to 2021). Sudden impairment of blood flow to a part of the brain due to occlusion or rupture of an artery to the brain. "Thus, AKAP7 may a clinically useful biomarker for the identification of patients at heightened risk for the development of post-stroke BBB disruption." (PMID 28446746, 2017). "To gain further insight into the possible functional role of AKAP7 in the context of post-stroke BBB disruption, we next looked to determine the cellular source of AKAP7 in the peripheral immune system." (PMID 28446746, 2017). "We feel these results provide valuable foundational knowledge which will allow for more in-depth exploration into AKAP7 as both a clinical biomarker and therapeutic target with regards to post-stroke BBB disruption." (PMID 28446746, 2017). "In terms of understanding the mechanistic role of AKAP7 in the peripheral immune system with regards to stroke pathophysiology, much of the analysis in this study was associative in nature and performed only at the level of transcription." (PMID 28446746, 2017). "This work yields novel insight regarding the biology of AKAP7 in the context of the peripheral immune system, and provides a foundation for further study regarding the role of AKAP7 in stroke pathology." (PMID 28446746, 2017). "The sample size in this study was not large enough to draw definitive conclusions regarding the potential use of AKAP7 as a clinical biomarker for prediction of post-stroke BBB complications." (PMID 28446746, 2017). "In addition to providing insight into the role of leukocyte AKAP7 in the context of stroke, this study generated novel data regarding the genomic regulation of AKAP7." (PMID 28446746, 2017). "Furthermore, like AKAP7, early expression levels of ITAG3 at were positively associated with the development of post-stroke severe HARM in a post-hoc logistic regression analysis controlling for age, dyslipidemia, and rtPA (p = 0.045*, Odds ratio = 3.5, 95% confidence interval = 1.0–28.4)." (PMID 28446746, 2017). "Expression levels of the PKA-binding AKAP7 isoforms appeared to be significantly higher on cells of lymphoid origin, leading us to hypothesize that AKAP7 levels may serve as a marker of post-stroke lymphocyte trafficking specifically." (PMID 28446746, 2017). "Furthermore, we show evidence that AKAP7 expression may be elevated in patients who later develop post-stroke BBB disruption as a result of the presence of an invasive lymphocyte population in peripheral circulation." (PMID 28446746, 2017). "Furthermore, early total expression levels of AKAP7 showed a modest ability to predict post-stroke BBB disruption, demonstrating 100% sensitivity (95% confidence interval = 63.1–100%) and 68.1% specificity (95% confidence interval = 43.5–87.0%) for the development of severe HARM." (PMID 28446746, 2017). "Furthermore, our findings suggest that AKAP7 is a marker for a highly adherent lymphocyte phenotype, and may be elevated in patients who later develop post-stroke BBB disruption as a result of the presence of an invasive lymphocyte phenotype in peripheral blood." (PMID 28446746, 2017). "Collectively these data suggest that AKAP7 expression is a marker of ITGA3-mediated lymphocyte adhesiveness and is likely elevated in patients who later develop post-stroke BBB disruption as a result of the presence of an invasive lymphocyte population in peripheral blood." (PMID 28446746, 2017). "Thus, our results suggest that AKAP7 and ITGA3 are molecules which could potentially be targeted therapeutically to limit lymphocyte-mediated post-stroke injury exacerbation." (PMID 28446746, 2017). "Thus, future work may want to address the possibility that non-lymphoid sources of AKAP7 may contribute to the whole blood elevation in expression levels observed with post-stroke BBB disruption." (PMID 28446746, 2017).
asthma (1 paper, 2020). "Concretely, four genes (ATF7IP, SLC43A3, AKAP7, HMGN1) were found to be correlated to pathogenesis or treatment of asthma in immune." (PMID 32948203, 2020).
heart failure (1 paper, 2023). Inability of the heart to pump blood at an adequate rate to meet tissue metabolic requirements. "For instance, the AAV-mediated expression of PLN-binding AKAPs or PKA-RII that preferentially binds AKAP7 can be a potential alternative treatment to increase SERCA activity in heart failure patients." (PMID 36766777, 2023).
lymph node metastasis (1 paper, 2023). "Immunohistochemistry showed that AKAP7 may be associated with the occurrence, clinical stages and grades, and lymph node metastasis of BLCA." (PMID 37123010, 2023). "In addition, immunohistochemistry showed that AKAP7 may be associated with the occurrence, progression and lymph node metastasis of BLCA." (PMID 37123010, 2023). "Therefore, we hypothesized that AKAP7 might be a marker in lymph node metastasis of BLCA." (PMID 37123010, 2023). "Therefore, it is speculated that AKAP7 and SLC1A6 play an important role in the occurrence of BLCA and lymph node metastasis." (PMID 37123010, 2023). "In addition, AKAP7 may be involved in the occurrence of BLCA and lymph node metastasis, which can inhibit the migration and invasion of cancer cells." (PMID 37123010, 2023).
tetanus (1 paper, 2016). A serious infectious disorder that follows wound contamination by the Gram-positive bacterium Clostridium tetani. "Since tetanus-induced LTP in the MF-CA3 pathway has previously been shown to be presynaptic and require PKA, we tested the possibility that compensation in AKAP7 KO mice might have produced a PKA-independent form of LTP." (PMID 27911261, 2016).
type 2 diabetic nephropathy (1 paper, 2019). "In these preliminary discovery experiments, we first implemented the iTRAQ technique to identify plasma gelsolin, collectin-11, PTPRJ, and AKAP-7 as candidate biomarkers in type 2 IDN, which will provide a useful basis for further analysis of the pathogenic mechanism of type 2 diabetic nephropathy." (PMID 31384238, 2019).
cancer (1 paper, 2023). A tumor composed of atypical neoplastic, often pleomorphic cells that invade other tissues. "In normal and cancer tissues, AKAP7 protein expression staining was mainly located in the cytoplasm, and partly in the nucleus." (PMID 37123010, 2023). "Due to the different expression level of AKAP7, the degree of staining of cancer and normal tissues was different." (PMID 37123010, 2023). "The result showed that AKAP7 was lowly expressed in cancer tissues." (PMID 37123010, 2023). "The results of immunohistochemistry also showed that AKAP7 was lowly expressed in cancer tissues." (PMID 37123010, 2023). "In vitro cell experiments showed that AKAP7 could also inhibit the migration and invasion of cancer cells." (PMID 37123010, 2023). "Moreover, with the increase of clinical stage and grade, immunohistochemistry showed that the expression level of AKAP7 in cancer tissues decreased." (PMID 37123010, 2023). "In addition, AKAP7 was found to inhibit the migration and invasion of cancer cells in vitro." (PMID 37123010, 2023). "Compared with paracancerous tissues, AKAP7, EFEMP1, EPN2 and LAMA2 were lowly expressed in cancer tissues, while RPS6KA1, SLC1A6, TRABD and ZNRD1 were highly expressed in cancer tissues." (PMID 37123010, 2023). "The cancer and paracancerous tissues of 18 clinical BLCA patients were collected to verify the expression of AKAP7 by qRT-PCR." (PMID 37123010, 2023).
heart diseases (1 paper, 2012). "Although the biological relationship between B4GALNT2 and human heart diseases has yet to be documented, AKAP7, DYRK1A and FAM19A2 have all been implicated in its etiology." (PMID 23176082, 2012).
infection (1 paper, 2016). The state of being infected such as from the introduction of a foreign agent such as serum, vaccine, antigenic substance or organism. "Cell lysates were prepared 18 hours post-infection, subjected to immunoprecipitation with an anti-AKAP7 antibody and any co-precipitating PKA subunits were detected via western blot with specific antibodies for each target." (PMID 27137912, 2016). "Disruption of the AKAP7-PKA interaction during infection required E1A and was dependent on the AKAP like domain in E1A." (PMID 27137912, 2016). "However, infection disrupted the endogenous interactions between AKAP7 and PKA." (PMID 27137912, 2016). "Infection with HAdV-5 did not alter the expression of AKAP7 or the various PKA subunits." (PMID 27137912, 2016).
tumours (1 paper, 2018). "Among these 20 common genes, the expression levels of CDK20, AKAP7, AZIN2, LIX1L, OSCP1, and SLFN12 were upregulated, while HLF was downregulated in TC-PD-L1+ tumours (Pattern 3 and Pattern 4)." (PMID 29921949, 2018).
AKAP7 also shares sentences with these, for which no sentence is quoted: alcoholic liver diseases (1 paper); cardiac hypertrophy (1); chronic hepatitis B (1); dyslipidemia (1); metastatic tumors (1).